SLC22A15 (solute carrier family 22 member 15)
Description:
Organic zwitterion/cation transporter with apparent specificity for amino acids and their derivatives. Has low affinity for its substrates and may regulate their flux across the plasma membrane at high substrate concentrations. Bidirectionally transports carnitine and acetylcarnitine, possibly regulating their cytosolic abundance and further fatty acid catabolism via beta oxidation. Displays high transport activity toward zwitterionic substrates such as glycine betaine and diet-derived ergothioneine and carnosine. Can transport cations having an indole skeleton such as thiamine with lower efficiency. Does not transport agmatine. The transport mechanism, symport with sodium or facilitated diffusion allosterically regulated by sodium, remains to be elucidated (Probable).
Synonyms: FLIPT1; PRO34686
Tractability: Small molecule: it belongs to a druggable protein family. Antibody: UniProt places it where antibodies can reach, with high confidence; its Gene Ontology location is reachable by antibodies, with high confidence; UniProt predicts a signal peptide or a membrane-spanning region.
Gene: Protein-coding gene on chromosome 1 (115,976,477 to 116,070,054, forward strand). Ensembl gene ENSG00000163393.
Subcellular location: Cell membrane
Pathways (Reactome):
Transport of small molecules: SLC-mediated transport of organic cations
Gene Ontology:
Molecular function: amino-acid betaine transmembrane transporter activity; transmembrane transporter activity
Biological process: amino-acid betaine transport; transmembrane transport
Cellular component: plasma membrane; membrane
Genetic constraint (gnomAD): Loss-of-function variants: 36 observed, 55.12 expected, observed/expected ratio (o/e) 0.65, 90% interval 0.5 to 0.86. The upper end of that interval is the gene's LOEUF score, 0.86, which puts it in group 3 of 6, group 1 being the genes least tolerant of losing a copy. Missense variants: 581 observed, 618.35 expected, observed/expected ratio (o/e) 0.94, 90% interval 0.88 to 1.01. Synonymous variants: 249 observed, 251.42 expected, observed/expected ratio (o/e) 0.99, 90% interval 0.89 to 1.1.
Homologues: Orthologues: chimpanzee SLC22A15 (99% identical), macaque SLC22A15 (99% identical), rat Slc22a15 (96% identical), pig SLC22A15 (95% identical), guinea pig SLC22A15 (94% identical), dog SLC22A15 (94% identical), mouse Slc22a15 (94% identical), rabbit SLC22A15 (92% identical), tropical clawed frog slc22a15 (59% identical), Drosophila melanogaster Orct (30% identical), Drosophila melanogaster Orct2 (30% identical), Caenorhabditis elegans K05F1.6 (27% identical), and 37 more. Paralogues in human: SLC22A4 (32% identical), SLC22A5 (30% identical), SLC22A7 (29% identical), SLC22A13 (29% identical), SLC22A2 (28% identical), SLC22A3 (28% identical), SLC22A1 (27% identical), SLC22A8 (27% identical), SLC22A16 (27% identical), SLC22A6 (27% identical), SLC22A12 (26% identical), SLC22A14 (23% identical), and 10 more.
Diseases named in the same sentence as SLC22A15 in open-access papers:
SLC22A15 is named in the same sentence as 10 diseases in open-access papers, as found by Europe PMC text mining. Sharing a sentence is not in itself a finding about the gene and the disease. The quoted sentences say what the papers report.
acute lymphoblastic leukaemia (1 paper, 2026). "Furthermore, the low level of true disease-specific changes simplifies identification of functionally relevant methylation changes, illustrated here by identification and functional confirmation of SLC22A15 as a tumour suppressor in acute lymphoblastic leukaemia." (PMID 41174288, 2026).
colorectal cancer (1 paper, 2024). A primary or metastatic malignant neoplasm that affects the colon or rectum. "According to current study, O-GlcNAcylation of YY1 targets SLC22A15 and AANAT, which promotes carcinogenesis in colorectal cancer cells." (PMID 39050579, 2024).
gout (1 paper, 2020). A condition characterized by painful swelling of the joints, which is caused by deposition of urate crystals. "rs146978188 is also in LD with an SNP of SLC22A15/FLIPT1, an orphan transporter gene in the same family as SLC22A12/URAT1, a well-known urate transporter gene that is strongly associated with gout." (PMID 32238385, 2020).
liver cancer (1 paper, 2022). An epithelial or non-epithelial malignant neoplasm that arises from the liver. "Finally, the mechanism of TRIM54 and SLC22A15 affecting liver cancer development through TAMs is still unclear, and further research was warranted." (PMID 36120553, 2022). "In our results, S100A9, SLC22A15, TRIM54, and PPARGC1A were identified as TIMGs, which were identified as prognostic biomarkers for liver cancer sufferers." (PMID 36120553, 2022). "Overall, S100A9, SLC22A15, TRIM54, and PPARGC1A were screened as TIMGs that can be used for prognostic prediction and be the potential targets of the ICI treatments for patients with liver cancer." (PMID 36120553, 2022).
pancreatic cancer (1 paper, 2026). "Although SLC22A15 has not previously been implicated in haematological malignancies, studies have suggested a potential role in colorectal, hepatocellular and pancreatic cancer." (PMID 41174288, 2026).
cancer (5 papers, 2022 to 2026). A tumor composed of atypical neoplastic, often pleomorphic cells that invade other tissues. "Concurrently, the protein level of S100A9, SLC22A15, and TRIM54 was found to be much higher in the cancer tissues or the cells around the blood sinus compared to the normal tissues." (PMID 36120553, 2022). "However, the SLC22A15 mRNA level was low or non-detectable in most cancers and cancer cell lines." (PMID 36768423, 2023).
tumour (2 papers, 2012 to 2026). "Expanding the analysis to identify DNA methylation events specific for individual B-cell malignancies allowed the identification of a larger number of candidate genes, including the identification of SLC22A15 as a novel tumour suppressor gene in ALL." (PMID 41174288, 2026).
SLC22A15 also shares sentences with these, for which no sentence is quoted: asthma (1 paper); colon cancer (1); osteoporosis (1).